IL6 (interleukin 6)
Diseases named in the same sentence as IL6 in open-access papers (continued):
Sharing a sentence is not in itself a finding about the gene and the disease.
leukemia (136 papers, 2007 to 2026). A malignant (clonal) hematologic disorder, involving hematopoietic stem cells and characterized by the presence of primitive or atypical myeloid or lymphoid cells in the bone marrow and the blood. "When JAK2 mutations or aberrant STAT activation occur in leukemia cells, they often lead to the upregulation of pro-inflammatory cytokines such as IL-6, IL-10, TNF-α, and GM-CSF." (PMID 40486651, 2025). "Neurocognitive dysfunction is associated with high IL-6 levels in patients with leukemia and myelodysplastic syndrome." (PMID 37760454, 2023). "Our results also indicated that the production of all tested cytokines, apart from IL-6, was reduced in leukemia-associated neutrophils." (PMID 37817276, 2023). "Remarkably, although each high-IL6/R genomic subtype is associated with high expression of a distinct set of leukemia-driving genes, all these genes activate the same set of signal transduction pathways." (PMID 36418348, 2022). "Bone marrow fibrosis, as well as multiorgan leukemia infiltration, was also substantially reverted with IL-6 deficiency." (PMID 35900794, 2022). "Given the observed upregulation of IL-6 in Pax5-deficient leukemic proB cells and mice, we next directly tested the requirement for IL-6 in Pax5-loss mediated leukemia growth in a system that recapitulates the spontaneous process of leukemogenesis." (PMID 33154497, 2020). "Although CRP is not thought to be directly associated with AML and chronic myeloid leukemia (CML), complications associated with leukemia, such as infections, and elevated systemic cytokines, such as IL-6, lead to elevated CRP levels." (PMID 29202702, 2017). "Similarly, to decrease the generation of the anti-apoptotic splicing variant Bcl-xL in K562 leukemia cells, interleukin-6 (IL-6) and granulocyte-macrophage colony-stimulating factor recognize distinct intronic sequences of the Bcl-x gene-encoded pre-mRNA." (PMID 40032844, 2025). "To determine whether IL-6 loss could also enhance the efficacy of PD-L1 blockade and promote anti-leukemia immune responses, we treated WT and IL-6 KO leukemic mice with PD-L1 inhibitors and monitored disease progression and survival." (PMID 34711820, 2021). "Leukemias at relapse showed similar recurrent mutations than leukemias before anti-IL-6-treatment." (PMID 33154497, 2020). "In addition, some experimental studies suggest that paracetamol is genotoxic to the bone marrow and could increase the risk of leukemia; third, laboratory evidence showed that paracetamol increases NF-κB induction and affects IL-6 transcription." (PMID 34070784, 2021). "IL-6 produced by leukaemia cells suppresses ADAMTS13 activity and impairs hematopoietic differentiation." (PMID 40671161, 2025). "The BCR/ABL fusion protein induces IL-6 expression in leukemia stem cells, and targeting IL-6R induces apoptosis in Philadelphia chromosome-positive acute lymphoblastic leukemia cells." (PMID 41293238, 2025). "In 3 patients, the baseline IL-6 level was <500 ng/L, and the indications for CytoSorb use were hyperbilirubinemia, rhabdomyolysis, and leukemia with capillary leak syndrome." (PMID 41140657, 2025). "Elevated levels of pro-inflammatory cytokines, particularly tumor necrosis factor-alpha (TNF-α), interleukin-6 (IL-6), and interleukin-17 (IL-17), are fundamental to both RA and leukemia progression." (PMID 41141147, 2025). "MSC also secrete a number of cytokines, chemokines, and growth factors (e.g., VEGFC, TGF‐β1, TGF‐ β2, GDF6, SDF1, and IL‐6) that can further modulate the interaction between leukemia cells and MSC." (PMID 40682336, 2025). "In AML, STAT3 from the nuclear extract of patient leukemia cells stimulated with IL-6 binds the probe of an IL-6 responsive element derived from the ICAM1 promoter." (PMID 39034990, 2024). "DHEAS can influence the inflammatory response by modulating the production of inflammatory factors such as TNF-α and IL-6, thereby impacting the progression of leukemia." (PMID 39351228, 2024).
leukemia (continued). "Inflammatory pathways mediated by interleukin (IL) 1b, IL-6, IL-1RAP, IL-8, and others lead to growth of aberrant leukemia and MDS stem and progenitors while inhibiting healthy hematopoiesis." (PMID 39319060, 2024). "There were also notable reductions in the leukemia-induced immunosuppressive cytokine milieu of Sig15 KO leukemia recipients, marked by decreases in IL6, LIF, and IL5 that all contribute to a more immune-privileged bone marrow niche." (PMID 37465593, 2023). "Skeletal muscle contributes to systemic effects by secreting cytokines and other myokines (including IL-6, IL-8, IL-15, and leukemia inhibitory factors) through local autocrine, paracrine, and endocrine actions." (PMID 37736552, 2023). "In contrast, IL-6 production was elevated, and these effects were restricted only to neutrophils at the late stage of leukemia." (PMID 37817276, 2023). "Increased amounts of cytokines, including the pro-inflammatory IL-6 and IL-8, altogether with the frequent infiltration of cancer cells in testis, has also been observed in patients affected by leukaemia." (PMID 37371875, 2023). "Elevated IL-6 levels, on the other hand, can slow leukemia progression by antagonizing TLR signaling." (PMID 35862190, 2022). "Together, these results reveal that IL-6 plays a major role in mediating MDS to leukemia progression in DKO mice." (PMID 35900794, 2022). "Elevated serum IL-6 levels, released by monocytes, macrophages, and T cells, have been reported in leukemia patients." (PMID 35204748, 2022). "Only IL-6 concentration increased significantly in both leukemia and head and neck carcinoma groups (p < 0.01 and p < 0.05, respectively)." (PMID 35476641, 2022). "An in vitro study also demonstrated that adlay bran extract reduced the excretion of TNFα and IL-6 in basophilic leukemia cells, which is consistent with our results." (PMID 35684050, 2022). "The authors also found that ssCART-19 cells produce lower levels of IL-6 and significantly reduce IL-6 secretion by monocytes in xenograft mouse model of leukemia." (PMID 34721401, 2021). "CNTF, which is a pluripotent neurotropic factor and is related with the cytokine family that includes IL-6, IL-11, leukemia inhibitory family, and oncostatin, binds and signals to maintain the bone homeostasis through the gp130 coreceptor subunit." (PMID 33833854, 2021). "While PD-L1 blockade exhibits modest efficacy in only a subset of WT mice, IL-6 KO mice undergo nearly complete leukemia eradication by 9 days after the initiation of PD-L1 blockade." (PMID 34711820, 2021). "Here, we find that production of IL-6 by the TME regulates chemotherapy efficacy in ALL by inhibiting anti-leukemia immunity." (PMID 34711820, 2021). "Here, we demonstrate that Pax5 heterozygosis, in the presence of infections, results in the enhanced production of the inflammatory cytokine interleukin-6 (IL-6), which appears to act in an autocrine fashion to promote leukemia growth." (PMID 33154497, 2020). "In order to further identify somatically acquired 2nd hits leading to leukemia development, we next performed whole exome sequencing of 4 IL-6+/-/Pax5+/- B-ALLs and corresponding germline on a HiSeq 2500 (Illumina) platform." (PMID 33154497, 2020). "The results showed that the reduction on IL-6 levels significantly delayed the emergency of leukemias in Pax5+/- mice upon exposure to natural infections." (PMID 33154497, 2020). "Consistent with our findings, recently, Zhou and colleagues also identified TEAD-binding sites in human IL6 promoter and showed direct regulation using a human leukemia monocytic cell line (THP-1 cells)." (PMID 33264286, 2020). "Surprisingly, we observed the same molecular sequence; TNF-α and IL-6 were simultaneously secreted in leukemia cells and in PBMCs following treatment with free DOX or the conjugate." (PMID 33321722, 2020).
leukemia (continued). "Last, we demonstrated that serum IL-6 levels were lower in a mouse xenograft model of leukemia after treatment with ssCART-19 cells than after treatment with regular CART-19 cells." (PMID 32523801, 2020). "We then characterized the global expression signature of IL-6+/-/Pax5+/- B-ALLs and compared it with the expression signature of both healthy WT pro-B/pre-B cells and IL-6+/+/Pax5+/- leukemias." (PMID 33154497, 2020). "Treatment of K562 leukemia cells with IL-6 resulted in a reduction in the Bcl-xL/Bcl-xS ratio; nucleotides 1–176 of the downstream intron were found to be required for the IL-6 effect." (PMID 31552099, 2019). "Here, the authors show that mesenchymal stem cells-derived PML is involved in the maintenance of leukemia cells through Cxcl1 and IL6 and that PML inhibition enhances sensitivity to chemotherapy." (PMID 29302031, 2018). "In both cell lines investigated, PsA-D incubation was able to induce a significant blockade of cytokine secretion: In THP-1 monocytic leukemia cells pseudopterosin reduced TNFα release by at least 47%, blocked IL-6 release by 50% and MCP-1 release by 73%." (PMID 28832545, 2017). "In this study, we show for the first time that cordycepin disrupts leukemia-MSC association through downregulation of N-cadherin in leukemia cells and attenuation of leukemia-CM-induced VCAM-1, IL-6 and IL-8 in MSCs." (PMID 28266575, 2017). "When LPHN1 is stimulated by its high-affinity ligand, α-latrotoxin (LTX), this significantly increases LPS-induced IL-6 release from leukaemia cell lines and primary cells." (PMID 27322212, 2016). "LPS was chosen to avoid TLR4 activation by endogenous ligands (such as proteins released after dysfunctionalisation of mitochondria), which themselves induce the expression and release of IL-6 and other important factors required for leukaemia cell survival." (PMID 27322212, 2016). "For example, leukemia inhibitor factor activates rabbit cardiac L-type Ca2+ channels, while IL-6 inhibits L-type Ca2+ channels in cerebellar granule neurons and prevents metabotropic glutamate receptor-activated Ca2+ signaling in cerebellar Purkinje neurons." (PMID 27010689, 2016). "We assessed the relationship between receptor expression levels and responses to each of the cytokines (IL-3, GM-CSF, IL-2, IL-4, M-CSF, G-CSF and IL-6) in leukemia cells from 11 patients with AML." (PMID 26375984, 2015). "Prior to our work, supernatants of FD leukemia samples containing IL-6 and IL-10, TNF-α, and IL-1β were shown to trigger a block in DC differentiation in vitro." (PMID 23616009, 2013). "The cells were then transfected with mRNA from the leukemia cell line Jurkat E6 by electroporation and incubated for additional 24 h or 2 days in the presence of pro-inflammatory cytokines (TNFα, IL-1β, IL-6 and PGE2) to obtain mature DCs." (PMID 17608923, 2007). "Actually, the sulfated polysaccharides isolated from T. suecica have been shown to exhibit anti-inflammatory activity against NO and IL-6, while those from Isochrysis galbana, which is a strain rich in glucans, inhibited the proliferation of human leukemia cells." (PMID 39997201, 2025). "For example, JAK2 mutations in leukemia cells can lead to the production of cytokines and growth factors such as IL-6, IL-10, and GM-CSF, which not only stimulate leukemia cell proliferation but also recruit immunosuppressive cells, like regulatory T-cells (Tregs), to the tumor microenvironment." (PMID 40486651, 2025). "IL‐6 knockout improves the efficacy of anti‐PD‐L1 blockade in the treatment of refractory leukemia." (PMID 37452653, 2024). "Concordantly, emerging evidence demonstrates that cancer cells release cytokines, extracellular vesicles, and exosomes, which have a potential role in altering the microenvironment at extramedullary sites, suggesting that CSF IL-6 is probably to be secreted by leukemia cells." (PMID 36531024, 2022).
leukemia (continued). "Interestingly, we find that IL-6 knock-out (KO) mice treated with doxorubicin completely clear leukemic cells, with the majority of these mice undergoing T-cell-dependent anti-leukemia immune responses and developing lasting immunologic memory." (PMID 34711820, 2021). "To test whether IL-6 can directly mediate resistance to doxorubicin, we cultured leukemia cells in the presence of IL-6, sIL-6R, or both IL-6 and sIL-6R to simulate signaling through sIL-6R-IL-6 complexes." (PMID 34711820, 2021). "In peritoneal macrophage and leukemia cell models, ginseng polysaccharide (GPS) stimulated macrophages to increase the levels of cytokines, including tumor necrosis factor-α (TNF-α), interleukin-1 (IL-1), IL-6, and nitric oxide (NO) production against leukemia." (PMID 34443587, 2021). "In addition, we found that the addition of exogenous IL-33 promotes the mRNA expression of the inflammatory cytokine, IL-6, in mouse leukemia cells by in vitro analysis." (PMID 33324412, 2020). "Previously, we demonstrated that exogenous IL-33 increases the expression of IL-6 using primary mouse leukemia cells expressing Cbfb-MYH11, which indicates that IL-33 may induce cytokine release to inhibit AML cell apoptosis." (PMID 33324412, 2020). "We next sought to examine whether IL-33 could enhance IL-6 release by leukemia cells using the same patient group." (PMID 33324412, 2020). "Together, our data suggest that IL-33 might work with IL-6 in the local and systemic circulation to support the maintenance of leukemia cells." (PMID 33324412, 2020). "BPA treatment in cell culture of a monocyte-like cell line derived from a leukemia patient and human peripheral blood macrophages have been found to release the proinflammatory cytokines TNFα and IL-6 and to decrease the anti-inflammatory/ regulatory cytokines IL-10 and TGFβ." (PMID 31551929, 2019). "Finally, we found that exposure of human leukemia cells to PM III not only caused cytotoxicity, but also mediated an intrinsic immune reaction via enhanced Interferon, Il-2, Il-6, and Il-10 signaling." (PMID 30486233, 2018). "Moreover, among the soluble factors regulated by Pml, Cxcl1, and Il6 seem to play an important role in the progression of the leukemia." (PMID 29302031, 2018). "We found that leukemia-CM may educate MSCs thereby inducing VCAM-1, IL-6, IL-8 and other effectors on promoting leukemia progression." (PMID 28266575, 2017). "However, incubation of THP-1 leukemia cells with stimulated M-CM induced a significant cytokine expression in THP-1 cells (8-fold increase of IL-6, 18-fold induction of TNFα and nearly 13-fold in MCP-1 expression)." (PMID 28832545, 2017). "Similarly, stimulation of the primary leukaemia cells with LTX leads to a substantial increase in the release of LPS-induced IL-6." (PMID 27322212, 2016). "Moreover, leukemia progression is significantly hampered in IL-6 knockout mice directly linking this cytokine to disease." (PMID 24952416, 2014). "Adventitial monocyte binding to AngII‐infused aorta in vitro was dependent on CD14, and incubation of human acute monocytic leukemia cell line‐1 (THP‐1) monocytes with IL‐6 or conditioned medium from perivascular adipose tissue (PVAT) upregulated CD14 expression." (PMID 23537804, 2013). "Furthermore, to assess if leukemia-induced decrease in miR-142 levels and activity of T cells could be rescued by blocking IL-6, we transplanted BM cells from Mir142−/−BCR-ABL mice (CD45.2) into congenic normal wt recipients (CD45.1, 106/mouse)." (PMID 39893171, 2025). "By inhibiting IL-6’s pro-inflammatory effects, including ICANS, this immunomodulatory drug could be a promising candidate for first-line use in patients at high risk of CRS, such as those with a high leukemia TB." (PMID 40176077, 2025).
leukemia (continued). "IL-6 promotes relapse in AML paediatric patients via supporting the leukaemia stem cells (LSCs) through inducing a STAT3 downstream signalling, that might enhance the survival and expansion of LSCs in the initial rounds of chemotherapy; thus, disease relapse occurs." (PMID 40671161, 2025). "Since MIR-574/3P gene is known to suppress proliferation and induces apoptosis of chronic myeloid leukemia (CML) cells via targeting IL6/JAK/STAT3 pathway, the findings of this study provide novel insights into the association of ADAM6 with miR-574-3p signaling pathway in leukemia." (PMID 34249950, 2021). "Next, to evaluate whether IL-6 KO mice develop lasting immunologic memory after doxorubicin treatment, we re-transplanted leukemia cells into previously cured IL-6 KO mice or naive controls and monitored leukemia progression." (PMID 34711820, 2021). "An important aspect that should be taken into consideration is that, although our data show that Pax5 indeed regulates IL6 expression, it cannot be rouled out that the microenvironment, following infections and/or leukemia, might also contribute to the observed IL6 increase." (PMID 33154497, 2020). "T cells expressing a chimeric antigen receptor (CAR) engineered to target CD19 can treat leukemia effectively but also increase the risk of complications such as cytokine release syndrome (CRS) and CAR T cell related encephalopathy (CRES) driven by interleukin-6 (IL-6)." (PMID 32523801, 2020). "Interestingly, in an animal model of leukemia that is characterized by cachexia, administration of an oral probiotic to restore Lactobacillus species reduced the expression of markers of atrophy in the muscles as well as inflammatory cytokines including IL-6." (PMID 30112118, 2018). "Incubation of the conditioned medium with anti-IL-6 antibody significantly attenuated the growth-promoting activity indicating that R-2HG released by AML cells increased the production of IL-6 from stromal cells to enhance the proliferation of leukemia cells via a paracrine stimulation." (PMID 27577048, 2016). "In our study, we found raised expression of IL-6, IL-17α, and TGF-β1 values both in the plasma and GCF of children with leukemia as compared to healthy subjects, while the levels of IL-1β were elevated only in the GCF." (PMID 41149097, 2025). "The results in our study are similar to these findings, with more elevated values of IL-6, both systemic (in plasma) and GCF, in children with leukemia, compared to the pediatric control group." (PMID 41149097, 2025). "A lipid nanoparticle system co-delivered the combination gene of interleukin 6 short hairpin RNA (IL-6 shRNA) and CD19-CAR (CAR19 shIL6) targeting leukemia with high CD19 expression." (PMID 40672956, 2025). "In this study, seven cytokines (IL1β, IL4, IL6, IL8, GM-CSF, TNFα, and VEGF) were measured in neonatal blood spots from 1,020 ALL cases and 1,003 controls in the California Childhood Leukemia Study." (PMID 39658797, 2024). "Further analysis of the conditioned media exhibited a marked reduction in interleukin-6 (IL-6) and IL-8 secretion when coculturing CD28KD or CD40LGKD T-ALL cells with HS-5 cells, demonstrating alterations in leukemia-infiltrated stromal microenvironment." (PMID 38233409, 2024). "The results demonstrated that pretreatment with OFI-EVs decreased the activity and gene expression of pro-inflammatory cytokines (IL-6, IL-8, and TNF-α) in the LPS-stimulated human leukemia monocytic cell line (THP-1)." (PMID 39000212, 2024). "Experiments with human monocytic leukemia cells (THP-1) revealed potential benefits of WPH on inflammation and endotoxin tolerance by modulating the immune response, and reducing IL-6 and IL-10 levels." (PMID 38594256, 2024). "The anti-inflammatory effects of mesalazine on the release of interleukin (IL)-6 and tumour necrosis factor alpha (TNF-α) were analysed using human leukemia monocytic cell line (THP-1)." (PMID 38474043, 2024).